IRX6 (iroquois homeobox 6)
Description:
Transcription factor. Binds to the iroquois binding site (IBS) motif of target genes to regulate gene expression; functions as a transcriptional activator or repressor. Modulates expression of RCVRN, VSX1, BHLHE22/BHLHB5 and TACR3/Nk3r. Required downstream of retinal bipolar cell specification for the terminal differentiation of type 2, type 3a and possibly type 6 bipolar cells.
Synonyms: IRX7; IRXB3; IRX-3
Tractability: No criterion of Open Targets' tractability assessment is met for any kind of drug.
Gene: Protein-coding gene on chromosome 16 (55,323,974 to 55,330,757, forward strand). Ensembl gene ENSG00000159387.
Subcellular location: Nucleus
Subcellular location (Human Protein Atlas): Mitochondria; Nucleoplasm
Gene Ontology:
Molecular function: protein binding; DNA-binding transcription factor activity, RNA polymerase II-specific; RNA polymerase II cis-regulatory region sequence-specific DNA binding; DNA binding
Biological process: cell development; neuron differentiation; regulation of transcription by RNA polymerase II; regulation of DNA-templated transcription
Cellular component: chromatin; nucleus
Genetic constraint (gnomAD): Loss-of-function variants: 45 observed, 46.98 expected, observed/expected ratio (o/e) 0.96, 90% interval 0.75 to 1.23. The upper end of that interval is the gene's LOEUF score, 1.23, which puts it in group 5 of 6, group 1 being the genes least tolerant of losing a copy. Missense variants: 719 observed, 613.1 expected, observed/expected ratio (o/e) 1.17, 90% interval 1.1 to 1.25. Synonymous variants: 265 observed, 256.84 expected, observed/expected ratio (o/e) 1.03, 90% interval 0.93 to 1.14.
Homologues: Orthologues: chimpanzee IRX6 (99% identical), macaque IRX6 (94% identical), pig IRX6 (81% identical), dog IRX6 (80% identical), guinea pig IRX6 (77% identical), rat Irx6 (74% identical), mouse Irx6 (73% identical), rabbit IRX6 (68% identical), zebrafish irx6a (45% identical), tropical clawed frog IRX6 (41% identical). Paralogues in human: IRX4 (41% identical), IRX1 (32% identical), IRX3 (31% identical), IRX2 (29% identical), IRX5 (28% identical), MKX (17% identical).
Diseases named in the same sentence as IRX6 in open-access papers:
IRX6 is named in the same sentence as 17 diseases in open-access papers, as found by Europe PMC text mining. Sharing a sentence is not in itself a finding about the gene and the disease. The quoted sentences say what the papers report.
hypospadias (3 papers, 2019 to 2025). Hypospadias is the displacement of the urethral meatus on the ventrum of the penis. "By performing a meta-analysis, we found a significant association between IRX6 rs6499755/HAAO rs3816183 with the increased risk of hypospadias (ORs = 1.46, p < 0.00001; ORs = 1.23, p < 0.00001, independently)." (PMID 40547448, 2025). "Three included studies assessed the association between the risk alleles [C] of IRX6 rs6499755 and the risk of hypospadias." (PMID 40547448, 2025). "Compared with the TT genotype, the CC phenotype of IRX6 rs6499755 was associated with the increased risk of hypospadias (CC vs. TT: OR = 2.234, 95% CI = 1.173–4.254, p=0.014)." (PMID 40547448, 2025). "In both case-control analysis and meta-analysis, the results revealed that the risk allele [C] of IRX6 rs6499755 increases the risk of hypospadias, which greatly increases the reliability of this kind of relationship." (PMID 40547448, 2025). "Recently, SNPs in HAAO and IRX6 genes were found to be associated with hypospadias in Japanese population." (PMID 31856834, 2019). "Through case-control analysis, we found that IRX6 rs6499755 was linked to an increased risk of hypospadias (OR = 1.547, p = 0.01), especially anterior (OR = 3.579, p=0.003) and posterior hypospadias (OR = 1.737, p=0.005), which probably through recessive models (OR = 1.832, p=0.026)." (PMID 40547448, 2025). "The risk allele [C] of IRX6 rs6499755 was associated with increased susceptibility to overall hypospadias (OR = 1.547, 95% CI = 1.108–2.160, p=0.01), anterior (OR = 3.579, 95% CI = 1.468–8.724, p=0.003) and posterior hypospadias (OR = 1.737, 95% CI = 1.179–2.560, p=0.005)." (PMID 40547448, 2025). "At the same time, the results showed that the IRX6 rs6499755 [C] polymorphism may be associated with hypospadias susceptibility in recessive models (CC vs. CT + TT: OR = 1.832, 95% CI = 1.072–3.130, p=0.026)." (PMID 40547448, 2025). "Our study indicates that there were associations between variations of IRX6 and HAAO and hypospadias risk in a Chinese Northern Han population." (PMID 40547448, 2025). "The result revealed a significant interaction between IRX6 rs6499755 and HAAO rs3816183 in the risk of hypospadias (cross-validation consistency = 10/10, testing balanced accuracy = 0.6065, p=0.0010)." (PMID 40547448, 2025). "The results of meta-analysis (including 3789 cases and 9241 controls) indicated that IRX6 rs6499755 and HAAO rs3816183 were significantly associated with hypospadias (both p < 0.00001)." (PMID 40547448, 2025). "GMDR analysis revealed a significant interaction between IRX6 rs6499755 and HAAO rs3816183 in the risk of hypospadias (cross-validation consistency = 10/10, testing balanced accuracy = 0.6065, p=0.0010)." (PMID 40547448, 2025). "Besides, more in-depth and comprehensive studies are needed to explore the biological pathogenic mechanism of IRX6 and HAAO leading to hypospadias." (PMID 40547448, 2025). "The meta-analysis supported the hypothesis that IRX6 rs6499755 and HAAO rs3816183 were the susceptibility loci for hypospadias." (PMID 40547448, 2025). "This case-control study was designed to investigate whether there is any meaningful relationship between IRX6 rs6499755 and HAAO rs3816183 polymorphisms with hypospadias in the Northern Han Chinese population, and try to find the corresponding risk alleles." (PMID 40547448, 2025). "Our study aims to investigate whether IRX6 rs6499755 and HAAO rs3816183 polymorphisms are susceptible to hypospadias in Chinese Northern Han." (PMID 40547448, 2025). "Moreover, GMDR analysis revealed a significant interaction between IRX6 rs6499755 and HAAO rs3816183 in the risk of hypospadias, which indicated the potential linkage disequilibrium." (PMID 40547448, 2025). "In the subgroup of anterior/middle hypospadias, we observed a not significantly related with IRX6 rs6499755(ORs = 1.30, p=0.06) and a significantly associated with HAAO rs3816183 (ORs = 1.39, p=0.0002)." (PMID 40547448, 2025).
hypospadias (continued). "Nevertheless, the further biological mechanisms of IRX6 rs6499755/HAAO rs3816183 result in the increased hypospadias risks remain unclear." (PMID 40547448, 2025). "Furthermore, the results of the meta-analysis support identified a strong relationship between the IRX6 and HAAO polymorphisms and hypospadias susceptibility in multiple populations." (PMID 40547448, 2025). "Although we did not include all possible proteins encoded by hypospadias risk associated genes (for example IRX5, IRX6, EYA1) for PPIs, our investigations indicated that disruption of SP1 and SP7 activity is associated with multiple known hypospadias risk associated genes in human via PPIs." (PMID 31856834, 2019).
breast carcinoma (1 paper, 2023). "Comparing trastuzumab-resistant (SKTR) and trastuzumab-sensitive (SK) HER2+ human breast cancer cell models, IRX6 was found to be a differentially methylated and differentially expressed gene, indicating a potential role in trastuzumab resistance." (PMID 36980893, 2023). "In luminal-B breast cancer tumor tissues compared with adjacent tissues, IRX6 was found to be the top 10 downregulated mRNA." (PMID 36980893, 2023).
cocaine dependence (1 paper, 2023). A psychologically and socially impaired state, with or without physiological changes, that develops as a result of using cocaine and which leads to compulsive behaviors to acquire the substance. "Other CU-associated CpGs worth noting includes cg09659661 on IRX6, which has been supported by other studies showing that the hypomethylation of IRX genes contributes to the development of cocaine dependence." (PMID 37730558, 2023).
colon adenocarcinoma (1 paper, 2023). "Decreased levels of IRX6 were observed in colon adenocarcinoma and rectum adenocarcinoma compared to normal tissues, and IRX6 had significant prognostic value in discriminating between high- and low-risk patients." (PMID 36980893, 2023).
heart failure (1 paper, 2023). Inability of the heart to pump blood at an adequate rate to meet tissue metabolic requirements. "According to the Genecards resource CES1 has a demonstrated role in cardiac conduction and cardiac drug metabolism while IRX6 is a potential hub gene in the pathogenesis of heart failure." (PMID 37277858, 2023).
posterior hypospadias (1 paper, 2025). Posterior hypospadias is a rare, non-syndromic, urogenital tract malformation characterized by an ectopic urethral meatus opening located in the posterior penis, the penoscrotal junction, the scrotum or the perineum, which often appears stenotic. "However, no significantly increased risk of posterior hypospadias was found linked to IRX6 rs6499755 [C] and HAAO rs3816183 [T] (all p > 0.05)." (PMID 40547448, 2025).
sarcoma (1 paper, 2022). A usually aggressive malignant neoplasm of the soft tissue or bone. "Other transcription factors associated with DEGs identified in the present study include FOXP2 and IRX6, neither of which has been well investigated in sarcomas." (PMID 36099287, 2022).
skin cutaneous melanoma (1 paper, 2023). "Higher expression of IRX1, IRX2, IRX3, IRX5, and IRX6 all display statistically significant unfavorable prognosis for skin cutaneous melanoma." (PMID 37084727, 2023).
cancer (2 papers, 2019 to 2023). A tumor composed of atypical neoplastic, often pleomorphic cells that invade other tissues. "IRX6 has not been well defined in cancer biology, particularly in CRC." (PMID 30627052, 2019).
neurological disease (1 paper, 2025). "ERRFI1, CTXN3, IRX6, and IQCA1 have not yet been reported in association with neurological disease." (PMID 40944498, 2025).
IRX6 also shares sentences with these, for which no sentence is quoted: Obesity (2 papers); cryptorchidism (1); endometrial cancer (1); epilepsy (1); Micropenis (1); rectum adenocarcinoma (1); virus infection (1).